MFN2 (mitofusin 2)
Description:
Mitochondrial outer membrane GTPase that mediates mitochondrial clustering and fusion. Mitochondria are highly dynamic organelles, and their morphology is determined by the equilibrium between mitochondrial fusion and fission events. Overexpression induces the formation of mitochondrial networks. Membrane clustering requires GTPase activity and may involve a major rearrangement of the coiled coil domains (Probable). Plays a central role in mitochondrial metabolism and may be associated with obesity and/or apoptosis processes (By similarity). Plays an important role in the regulation of vascular smooth muscle cell proliferation (By similarity). Involved in the clearance of damaged mitochondria via selective autophagy (mitophagy). Is required for PRKN recruitment to dysfunctional mitochondria. Involved in the control of unfolded protein response (UPR) upon ER stress including activation of apoptosis and autophagy during ER stress (By similarity). Acts as an upstream regulator of EIF2AK3 and suppresses EIF2AK3 activation under basal conditions (By similarity).
Synonyms: CPRP1; KIAA0214; MARF; CMT2A2; CMT2A; CMT2A2A; CMT2A2B; HMSN6A; HSG; MSL
Tractability: Small molecule: a structure with a bound ligand is known; a high-quality ligand is known. Antibody: UniProt predicts a signal peptide or a membrane-spanning region. PROTAC: UniProt records ubiquitination sites on it; ubiquitination databases record sites on it; its protein half-life has been measured; a small molecule that binds it is known.
Target class: Enzyme; Hydrolase
Gene: Protein-coding gene on chromosome 1 (11,980,181 to 12,015,211, forward strand). Ensembl gene ENSG00000116688.
Subcellular location: Mitochondrion outer membrane
Subcellular location (Human Protein Atlas): Mitochondria
Pathways (Reactome):
Autophagy: PINK1-PRKN Mediated Mitophagy
Hemostasis: Factors involved in megakaryocyte development and platelet production
Signal Transduction: RHOT2 GTPase cycle
Gene Ontology:
Molecular function: GTPase activity; protein binding; ubiquitin protein ligase binding; GTP binding
Biological process: aerobic respiration; mitochondrial fusion; mitochondrial membrane organization; negative regulation of Ras protein signal transduction; positive regulation of vascular associated smooth muscle cell apoptotic process; positive regulation of vascular associated smooth muscle cell proliferation; protein localization to phagophore assembly site; mitochondrion localization; negative regulation of smooth muscle cell proliferation; positive regulation of cold-induced thermogenesis; type 2 mitophagy; mitochondrion organization
Cellular component: mitochondrial outer membrane; mitochondrion; cytosol; membrane; microtubule cytoskeleton
Genetic constraint (gnomAD): Loss-of-function variants: 43 observed, 92.12 expected, observed/expected ratio (o/e) 0.47, 90% interval 0.37 to 0.6. The upper end of that interval is the gene's LOEUF score, 0.6, which puts it in group 2 of 6, group 1 being the genes least tolerant of losing a copy. Missense variants: 743 observed, 1,026.2 expected, observed/expected ratio (o/e) 0.72, 90% interval 0.68 to 0.77. Synonymous variants: 337 observed, 379.29 expected, observed/expected ratio (o/e) 0.89, 90% interval 0.81 to 0.97.
Homologues: Orthologues: chimpanzee MFN2 (99% identical), macaque MFN2 (99% identical), dog MFN2 (97% identical), guinea pig MFN2 (97% identical), pig MFN2 (96% identical), rat Mfn2 (95% identical), mouse Mfn2 (95% identical), rabbit MFN2 (93% identical), tropical clawed frog mfn2 (85% identical), zebrafish mfn2 (83% identical), Drosophila melanogaster Marf (47% identical), Caenorhabditis elegans fzo-1 (35% identical). Paralogues in human: MFN1 (62% identical).
Diseases named in the same sentence as MFN2 in open-access papers:
MFN2 is named in the same sentence as 314 diseases in open-access papers, as found by Europe PMC text mining. Sharing a sentence is not in itself a finding about the gene and the disease. The quoted sentences say what the papers report.
Obesity (70 papers, 2011 to 2026). Accumulation of substantial excess body fat. "Conversely, the effect in POMC neurons is entirely different, with Mfn2 deficiency causing severe obesity, binge eating, and endocrine disorders." (PMID 39763653, 2024). "Reduced MFN2 expression has been linked to decreased mitochondrial function in subcutaneous and visceral adipose tissues of individuals with obesity." (PMID 38928386, 2024). "The co‐IP assay in human myocardium revealed decreased binding of Mfn2 with Hsc70 in the hearts of patients with obesity, which was associated with increased Mfn2 acetylation and ubiquitylation." (PMID 38311582, 2024). "Deficiency of MFN2 has been associated with various myopathies, including obesity, diabetes, cancer, Alzheimer’s, and Parkinson’s diseases." (PMID 36765117, 2023). "MFN2 mutations are also associated with many other conditions, such as Alzheimer’s disease, Parkinson’s disease, obesity, and diabetes." (PMID 37724949, 2023). "Mutations of MFN1 and MFN2 are related to the development of neurological diseases, obesity, and vascular diseases." (PMID 36743936, 2022). "Obesity-induced MFN2 repression was also associated with the decline of mitochondrial ETC complexes I, II, III, and V." (PMID 34708072, 2021). "Deleting Mfn2 from murine satiety-promoting pro-opiomelanocortin (POMC)-producing neurons of mice led to extreme obesity, which was associated with mitochondrial morphological changes, including fewer MFN2-dependent MERCs." (PMID 34114603, 2021). "Apart from its major involvement in mitochondrial fusion, dysfunction of Mfn2 is associated with various pathological conditions, including diabetes type 2 and obesity." (PMID 31178957, 2019). "These confirm the crucial regulatory role of Mfn2 in insulin signaling and glucose homeostasis associated with obesity and T2D." (PMID 31551926, 2019). "Changes in Mfn2 expression due to altered glucose oxidation in conditions such as diabetes, obesity, insulin resistance, exercise and weight loss, have been demonstrated both in vitro and in vivo." (PMID 29068134, 2018). "Loss of Mfn2 protects from diet‐induced obesity only at 22°C and from insulin resistance at both 22°C and thermoneutrality." (PMID 28539390, 2017). "Reduced expression of Mfn1 and/or Mfn2 in skeletal muscle has been linked to obesity and type 2 diabetes mellitus in both rodents and humans." (PMID 29257072, 2017). "Given that Mfn2 defect contributes to metabolic defects associated with obesity, neuropathy, as well as cardiac dysfunction, it is understandable that Mfn2-deficiency leads to the inhibition of cell proliferation." (PMID 25781899, 2015). "A shift toward mitochondrial fission with reduction of fusion protein, mainly mitofusin 2, has been associated with reduced insulin sensitivity and inflammation in obesity and IR development." (PMID 26834644, 2015). "Conversely in anorexigenic pro-opiomelanocortin POMC neurons, Mfn2 selective deletion causes severe obesity and leptin resistance probably by mediating ER stress-induced leptin resistance." (PMID 25904870, 2015). "Mutations of Mfn2 are causally linked with autosomal dominant neurodegenerative disease Charcot-Marie-Tooth type 2A, obesity and type 2 diabetes." (PMID 25781899, 2015). "In recent years, hypothalamic ER stress has emerged as a causal factor in the development of leptin resistance and obesity and this study established Mfn2 as a key molecular determinant connecting these processes." (PMID 26113818, 2015). "Deficiency of Mfn2 inhibited the expression of ETC complexes I/II/III/V and caused neuropathy and obesity, this is in general agreement with our present results that Mfn2 knockdown reduced mitochondrial oxygen consumption rate." (PMID 25781899, 2015). "It has been shown that obesity induces Mfn2 deficiency which results in reduced mitochondrial activity, and Drp1 deletion leads to reduction of mtDNA content." (PMID 25543537, 2014).
Obesity (continued). "Loss or down-regulation of Mfn2 expression has been found in energy dysmetabolism-related diseases, such as obesity and diabetes." (PMID 24898700, 2014). "Additionally, suppression of MFN2 in skeletal muscle from patients with obesity and T2DM has been associated with the development of insulin resistance." (PMID 41481647, 2026). "In obesity, mitochondrial fragmentation is associated with a decrease in MFN2 in skeletal muscle." (PMID 39519269, 2024). "On the other side, upregulation of MFN2 attenuates the CH induced by angiotensin II, and complementarily; in diabetes and obesity, which are conditions correlated with an increased risk of CVDs, MFN2 expression is downregulated, and can be recovered with weight loss and exercise." (PMID 36187489, 2022). "This suggests that improving the expression levels of Mfn2 in obese patients may help to treat male or female infertility caused by obesity." (PMID 35725948, 2022). "Aside from its main participation in mitochondrial fusion, mitochondrial morphology, and mitochondrial function, dysfunction of this Mfn2 is also linked with an assortment of pathological conditions, such as Charcot–Marie–Tooth disease type 2A, diabetes mellitus type 2, obesity, and cancer." (PMID 30410558, 2018). "The region contains the MFN2 gene (Mitofusin 2), which encodes a mitochondrial membrane protein involved in the regulation of muscle cell proliferation, and it plays a role in the pathophysiology of obesity." (PMID 29522525, 2018). "The pro-opiomelanocortin (POMC) neuronal-specific Mfn2 ablation in mice caused hyperphagia, reduced energy expenditure, endoplasmic reticulum stress-induced leptin resistance and obesity, indicating that Mfn2 plays a vital role in maintaining systemic energy balance." (PMID 29257072, 2017). "Moreover, in diet induced obese mice, it was shown a decrease in mitochondrial network complexity and in mitochondria-ER association due to a reduction in Mfn2 expression in the hypothalamus which precedes the onset of obesity." (PMID 25904870, 2015). "Therefore, it has been suggested that Mfn2 loss-of-function found in obesity conditions enhance bioenergetics efficiency and contribute to obesity development by reducing energy expenditure and increasing fat energy store." (PMID 25904870, 2015). "Moreover, MFN2 has been linked with diabetes and obesity, which are, per se, intimately related." (PMID 31156446, 2019). "Also, obesity leads to changes in mitochondrial morphology in liver and increases ER-mitochondria junctions, suggesting that MFN2 regulation might influence susceptibility to gain more weight during growth and metabolic dysfunction." (PMID 29991958, 2018). "Consequently, these data together with the mitochondrial respiratory profile suggest that resistance to obesity and better insulin sensitivity induced by Mfn2 deletion in BAT is linked to increased coupled fatty acid oxidation in BAT and, possibly, in other tissues." (PMID 28539390, 2017). "Repression of Mfn2 reduced glucose oxidation, mitochondrial membrane potential, cell respiration, and mitochondrial proton leak and reduced Mfn2 expression may explain some of the metabolic alterations associated with obesity." (PMID 23443131, 2012). "Mechanistic studies implicate mitochondrial dysfunction and endoplasmic reticulum (ER) stress as key contributors, exemplified by POMC-specific Mitofusin 2 (Mfn2) deletion, which induces ER stress, leptin resistance, and obesity." (PMID 41409607, 2025). "Multiple studies have reported reduced MFN2 levels in the context of obesity, diabetes, and high-fat diets in the SM, and modulation of its expression can reverse, prevent, or ameliorate SM mitochondrial function." (PMID 40723425, 2025). "Mice in which Mfn2 was inducibly deleted in all adipocytes in adulthood showed increased obesity and elevated blood glucose." (PMID 39739772, 2024).
Obesity (continued). "The study also found that obesity and insulin resistance can be induced by adipocyte-selective inducible ablation of Mfn2 in mice." (PMID 38928386, 2024). "Reduction in MFN2 levels has been demonstrated in muscle and liver of diet‐induced obesity models, prompting us to examine β‐cell MFN2 levels in islets isolated from two obesity models: high‐fat diet (HFD)‐fed mice and Zucker rats." (PMID 36917141, 2023). "The fusion of outer membranes during mitochondrial fusion is controlled by mitofusion proteins 1 and 2 (Mfn1/Mfn2), and obesity downregulates Mfn2 gene expression." (PMID 36918975, 2023). "Mice in which Mfn2 was deleted in all adipocytes in adulthood showed increased obesity and elevated blood glucose." (PMID 36722855, 2023). "Mfn2 deletion in these neurons prevents these adverse metabolic effects: fat mass was reduced, insulin and glucose levels were legitimized, and obesity was avoided." (PMID 35898328, 2022). "Diminished expression of MFN2 is regarded as an important factor in the induction of mitochondrial dysfunction in the course of obesity and T2D." (PMID 33815291, 2021). "In a different study, Dietrich and colleagues observed a role for both Mfn1 and Mfn2 in diet-induced obesity by studying the hunger-promoting Agouti-related protein (Agrp) neurons." (PMID 34114603, 2021). "Agents reported to target the mitochondrial fission factor DRP1 or to up‐regulate the fusion factor MFN2 have been evaluated in obesity models." (PMID 34231322, 2021). "Selective ablation of Mfn2 from POMC neurons in mice (POMCMfn2KO) caused leptin resistance, hyperphagia, and a reduction in energy expenditure and obesity." (PMID 33240218, 2020). "Proopiomelanocortin neurons-specific ablation of Mfn2 resulted in ER stress-induced leptin resistance, hyperphagia, reduced energy expenditure, and obesity." (PMID 29491355, 2018). "Recently, using brown adipose tissue-specific Mfn2 knockout mice it was demonstrated that Mfn2 is crucial for thermogenesis, and when fed a high-fat diet, these mice are protected against insulin resistance, hepatic steatosis and obesity." (PMID 29257072, 2017). "This led us to test the effects of diet‐induced obesity on Mfn2 expression and specifically on BAT mitochondria oxidative capacity." (PMID 28539390, 2017). "Our study identified for the first time a role for Mfn2 in the response of BAT to obesity and in a gender dependent manner." (PMID 28539390, 2017). "To determine the contribution of diet‐induced upregulation of Mfn2 to obesity and glucose intolerance, we deleted Mfn2 specifically in brown adipocytes by generating a BAT‐specific Mfn2 KO." (PMID 28539390, 2017). "Our research group has observed previously that melatonin supplementation significantly improved the obesity induced renal alterations, restoring mitochondrial shape and Mfn2 expression." (PMID 29206172, 2017). "To best define the mitochondrial morphological alteration in obesity, we observed a correlation between Mfn2 expression and the cytoarchitecture of mitochondria and their cristae in proximal tubules." (PMID 25347680, 2014). "Silencing of Mfn-2 substantially impairs metabolic parameters, and animal models of obesity show a marked reduction of Mfn-2 levels in muscle cells." (PMID 25566542, 2014). "Mfn2 expression is down-regulated in the Zucker rat model of obesity and in human subjects with obesity or diabetes." (PMID 21448454, 2011). "However, further studies are needed to clarify the different regulatory mechanisms of Mfn1, Mfn2, and Drp1 targeting mitochondrial metabolism in diabetes and obesity." (PMID 37942520, 2025). "In a rat model of insulin resistance and obesity, empagliflozin regulates mitochondrial dynamics, increasing fusion protein mitofusin-2 (MFN2) expression, while decreasing the levels of the fission protein dynamin-related protein 1 (DRP1) in white adipose tissue." (PMID 40072115, 2025).
Obesity (continued). "As a proof-of-concept, we showed that disrupting Mfn2 expression in astrocytes reduced their ability to support dynamic circuit reorganization, a time-locked feature of satiety in the hypothalamus, thus leading to obesity in mice." (PMID 38405925, 2024). "Tissue-specific deletion of mitofusin-2 (Mfn2) in muscles of mice disrupts glucose homeostasis, and Drp1 ablation in the liver results in reduced adiposity and elevated whole-body energy expenditure, protecting mice from diet-induced obesity." (PMID 38464536, 2024). "Additionally, we observed the inhibition of MLC and a decrease in Mfn2 levels in Pal‐treated hiPSC‐CMs and cardiac tissue from patients with obesity." (PMID 38311582, 2024). "Compared with sarcopenia or obesity alone, myopenic obesity is more likely to increase the risk of death, and patients with myopenic obesity have significantly lower expression of mitochondria-related proteins PGC-1α, MFN1, MFN2 and DRP1 than normal controls." (PMID 37495991, 2023). "Furthermore, deletion of the mitochondrial protein, Mfn2, in brown adipose tissue protected from insulin resistance and obesity, despite impairing cold-induced thermogenesis." (PMID 34741717, 2022). "Strikingly, humans with obesity exhibit a reduction in the expression levels in Mfn2." (PMID 35725948, 2022). "The authors further found that MFN2 was repressed under obesity." (PMID 34708072, 2021). "Hyperleptinemia may itself stem from excessive mitochondria fission; eliminating the mitochondrial fusion mediator MFN2 from adipocytes is sufficient to produce hyperleptinemia and obesity." (PMID 34231322, 2021). "This may reflect an early, initial stage in obesity development because just 4 days of HFD feeding in the absence of significant weight gain was enough to downregulate hypothalamic Mfn2 mRNA." (PMID 33092099, 2020). "Patients with T2DM and obesity demonstrated reduced expression of Mfn2, which may be related to the reduced function of mitochondria." (PMID 32104528, 2020). "Besides, it was first reported that proopiomelanocortin (POMC)–specific ablation of Mfn2 results in endoplasmic reticulum (ER) stress–induced leptin resistance and decreased energy expenditure for protection against obesity." (PMID 31551926, 2019). "However, further studies should determine the distinct regulatory mechanisms of Mfn1 and Mfn2 targeting mitochondrial metabolism in diabetes and obesity." (PMID 31551926, 2019). "In obesity and type II diabetes, MFN2 expression has been found to be reduced." (PMID 29491355, 2018). "In addition, Mfn2 expression was downregulated in mouse POMC neurons as early as 4 days after high fat diet‐induced obesity." (PMID 29068134, 2018). "Additionally, liver MFN2 levels are decreased in obesity, but increased by increasing HO-1 levels, thereby reducing the severity of NASH." (PMID 30057822, 2018). "Previous works showed that MFN2 expression is reduced in patients with obesity or type 2 diabetes as well as in obese Zucker rats, a model of type 2 diabetes, suggesting that mitochondrial fusion is an important factor in the pathophysiology of these disorders." (PMID 29351809, 2018). "To address our hypothesis, we tested the effects of diet‐induced obesity on the mitochondrial fusion protein Mfn2 and on the oxidative function of BAT mitochondria." (PMID 28539390, 2017). "Furthermore, it suggests that BAT lipohypertrophy induced by obesity can be a regulated response protecting from insulin resistance 5, which has higher efficiency with Mfn2 deleted." (PMID 28539390, 2017). "In the context of this newly identified pathway, we hypothesized that obesity can induce changes in BAT mitochondrial dynamics through Mfn2, thereby affecting energy expenditure and, through that, insulin sensitivity and glucose homeostasis." (PMID 28539390, 2017). "Therefore, thermoneutrality largely removed the protective effect induced by Mfn2 deletion on obesity." (PMID 28539390, 2017).